HOXC12 (homeobox C12)
Description:
Sequence-specific transcription factor which is part of a developmental regulatory system that provides cells with specific positional identities on the anterior-posterior axis.
Synonyms: HOC3F; HOX3F; HOX3
Tractability: No criterion of Open Targets' tractability assessment is met for any kind of drug.
Gene: Protein-coding gene on chromosome 12 (53,954,903 to 53,958,956, forward strand). Ensembl gene ENSG00000123407.
Subcellular location: Nucleus
Gene Ontology:
Molecular function: sequence-specific double-stranded DNA binding; DNA binding; DNA-binding transcription factor activity, RNA polymerase II-specific
Biological process: regulation of DNA-templated transcription; regulation of transcription by RNA polymerase II
Cellular component: nucleus
Genetic constraint (gnomAD): Loss-of-function variants: 24 observed, 16.56 expected, observed/expected ratio (o/e) 1.45, 90% interval 1.04 to 1.89. The upper end of that interval is the gene's LOEUF score, 1.89, which puts it in group 6 of 6, group 1 being the genes least tolerant of losing a copy. Missense variants: 436 observed, 370.53 expected, observed/expected ratio (o/e) 1.18, 90% interval 1.09 to 1.27. Synonymous variants: 202 observed, 172.02 expected, observed/expected ratio (o/e) 1.17, 90% interval 1.05 to 1.32.
Homologues: Orthologues: chimpanzee HOXC12 (99% identical), macaque HOXC12 (98% identical), pig HOXC12 (98% identical), guinea pig HOXC12 (97% identical), rabbit HOXC12 (96% identical), rat Hoxc12 (96% identical), mouse Hoxc12 (95% identical), dog HOXC12 (93% identical), tropical clawed frog hoxc12 (71% identical), zebrafish hoxc12a (67% identical), zebrafish hoxc12b (53% identical). Paralogues in human: HOXD12 (41% identical), HOXA10 (27% identical), HOXD9 (26% identical), HOXC10 (25% identical), HOXD10 (25% identical), HOXC9 (24% identical), HOXB9 (24% identical), HOXC11 (21% identical), HOXA13 (19% identical), GSX2 (19% identical), HOXA1 (18% identical), HOXB1 (18% identical), and 30 more.
Diseases named in the same sentence as HOXC12 in open-access papers:
HOXC12 is named in the same sentence as 23 diseases in open-access papers, as found by Europe PMC text mining. Sharing a sentence is not in itself a finding about the gene and the disease. The quoted sentences say what the papers report.
breast carcinoma (2 papers, 2014 to 2024). "An intriguing observation in breast cancer tissues is that increased DNA methylation in an intergenic CpG island located between HOXC12 and HOTAIR is positively correlated with HOTAIR expression in breast cancer." (PMID 25491133, 2014).
clubfoot (2 papers, 2023 to 2025). The most common congenital deformation of the foot, occurring in 1 of 1,000 live births. "Recent findings have also highlighted HOXC microdeletions overlapping a noncoding region upstream of HOXC13, alongside a point mutation in HOXC11 segregating within a family affected by isolated clubfoot, and another point mutation in HOXC12 that is prevalent among clubfoot patients." (PMID 40746736, 2025). "A missense SNP in HOXC11 in a family with an isolated form of clubfoot and a missense SNP in HOXC12 in clubfoot patients have been reported." (PMID 37964341, 2023).
bladder cancer (1 paper, 2015). "MCF7 generally displayed higher expression of posterior HOXC genes compared to bladder cancer cell lines, including HOXC12 which is silenced in most UC cells." (PMID 25994132, 2015).
breast tumor (1 paper, 2021). "The expression level of HOXC12 is increased in breast tumor samples and TLX1 shows misregulation in cancer." (PMID 34470627, 2021).
endometriosis (1 paper, 2021). The growth of functional endometrial tissue in anatomic sites outside the uterine body. "We suggest knock out the upregulated genes with extensive fold changes like HOXC12 in endometriosis organoids and over-express these genes in endometrial organoids developed from non-endometriosis patients to explore the role of these genes in the development of endometriosis." (PMID 34470627, 2021).
follicular lymphoma (1 paper, 2016). Follicular lymphoma is a form of non-Hodgkin lymphoma characterized by a proliferation of B cells whose nodular structure of follicular architecture is preserved. "HOXC12 is repressed in follicular lymphoma through hypermethylation of its promoter, and has also been implicated in the differentiation of follicle cells, both of which suggest a possible function in tumor suppression." (PMID 26867567, 2016).
gastric adenocarcinoma (1 paper, 2023). "A previous bioinformatics analysis revealed that HOXC genes (HOXC8, HOXC9, HOXC10, HOXC11, HOXC12, and HOXC13) might participate in pathogenesis of gastric adenocarcinoma." (PMID 37724126, 2023).
glioma (1 paper, 2021). A benign or malignant brain and spinal cord tumor that arises from glial cells (astrocytes, oligodendrocytes, ependymal cells). "For instance, the CGI/promoters of HOXB1 and HOXC12, two genes that were not expressed in glioma samples, were marked by a combination of H3K27me3‐only and DNA methylation." (PMID 33720519, 2021). "Moreover, several of them (e.g., HOXA1, A5, A6, A7, A10, D9, and D10) were expressed in most IDHwt glioma samples, constituting thus the core HOX signature in IDHwt samples, whereas HOXB1, HOXC12, HOTTIP, and HOXB‐AS4 were not reactivated." (PMID 33720519, 2021).
lung carcinoma (1 paper, 2022). "At the genomics level, researchers from Iran in 2019 reported that a SNP in gene HOXC12 is associated with risk of multiple cancer subtypes, implying the specific lung cancer driver potentials of this gene." (PMID 35155435, 2022). "Several genes, such as HOXC12, HAND1, VIPR2, KRT20, MMP24, and VIPR2, were discovered, and their special roles at different omics levels of lung cancer were confirmed." (PMID 35155435, 2022).
mesothelioma (1 paper, 2016). A usually malignant and aggressive neoplasm of the mesothelium which is often associated with exposure to asbestos. "One of the most striking differences is the expression of HOXC12 and HOXD12 by Met-5a but not by any of the mesothelioma cell lines." (PMID 26867567, 2016).
prostate carcinoma (1 paper, 2018). A carcinoma that arises from epithelial cells of the prostate gland. "Notably, they included DMRs close to many genes previously implicated in prostate cancer (e.g., NEAT1, MTOR, RHCG, KCNC2, WT1, HOXC12, KMT2B)." (PMID 30318509, 2018).
tumor (7 papers, 2016 to 2025). "Among them, HOXC11, HOXC10, HOXC8, and HOXC12 interact with HOTAIR in gastrointestinal tumors to jointly promote tumor formation and development." (PMID 36924407, 2023). "However, other genes, such as HOXB1, HOXC5, HOXC12, HOXD3, and HOXD12, have extremely low expression levels, suggesting that they are more expressed in normal tissue samples than in tumor samples." (PMID 39980564, 2025). "Compared with the normal tissues, most of the HOX genes showed increased expression in tumor tissues, only HOXB1 and HOXD1 decreased expression in PGs samples, and the difference in expression of these HFGs in normal and tumor tissues was statistically significant except HOXB8 and HOXC12." (PMID 37547473, 2023).
cancer (5 papers, 2018 to 2025). A tumor composed of atypical neoplastic, often pleomorphic cells that invade other tissues. "HOXC12 has never been found to be aberrantly expressed in solid tumors, suggesting that HOXC12‐overexpressing cancer cells might be counterselected." (PMID 33720519, 2021).
HOXC12 also shares sentences with these, for which no sentence is quoted: brain disorder (1 paper); gastric cancer (1); gastrointestinal tumors (1); hepatocellular carcinoma (1); leukemia (1); Obesity (1); osteosarcoma (1); ovarian carcinoma (1); pancreatic tumors (1); retinoblastoma (1).